TNF (tumor necrosis factor)
Diseases named in the same sentence as TNF in open-access papers (continued):
Sharing a sentence is not in itself a finding about the gene and the disease.
infection (continued). "Type I cytokines such as IL-2, IFN-γ, and TNF-α increased gradually in the sera of both the RH and ME49 groups, and there was an earlier significant increase of IFN-γ at day 3 post-infection in the RH group (RH group vs. Control group: 12.74 ± 1.15 vs. 4.33 ± 0.88, P < 0.05)." (PMID 30564216, 2018). "The levels of many inflammatory cytokines, including IFNγ and TNFα, did not change or minimally changed throughout infection." (PMID 30596671, 2018). "Our comparisons of tofacitinib versus non-TNF biologics, though not definitive, did not clearly demonstrate differences with respect to hospitalized infections." (PMID 29566769, 2018). "This is the first demonstration that this new form of anti-TNF therapy has the potential to be used in the treatment of infection-induced pathogenesis as well as non-infectious inflammatory conditions." (PMID 29636466, 2018). "In the next round of infection this led to the alteration of early events in lytic replication including the deposition of the ORF75C tegument protein, the accelerated kinetics of viral gene expression, and induction of TNFα release and cell death." (PMID 29390024, 2018). "In comparison, the expression of IL-1β, TNF-α, and IL-6 is not markedly changed 12 h after infection, which is markedly increased 24 h and 48 h after infection." (PMID 30186539, 2018). "Our group previously found increased TNFα production measured by ELISA in response to stimulation with DENV antigen by PBMC collected before infection in children who were hospitalized versus not hospitalized during the subsequent secondary DENV infection." (PMID 30557313, 2018). "Based on the varying trends of serum TNF-α and IFN-γ levels during infection by different pathogens, this finding may be useful for distinguishing pathogens in clinical settings." (PMID 30275916, 2018). "Here, treatment of the infected macrophages with various concentrations of mouse recombinant TNFα failed to activate macrophages for the killing of intracellular Leishmania and to reduce the initial infection rate." (PMID 30108591, 2018). "Interestingly, only three cytokines increased in levels throughout duration of infection: IL-2, IL-4, and TNFα, the latter being important for DENV-3 C0360/94 infection of AG129 mice." (PMID 29559699, 2018). "Among JIA patients, the infection rates did not increase with MTX or TNF-inhibitor use, but was significantly increased with at least a moderate dose of glucocorticoids." (PMID 30412634, 2018). "Remarkably, Psae-induced pro-inflammatory immune responses were not restricted to the gut, but could also be observed systemically as indicated by increased TNF and IFN-γ concentrations in sera upon Psae-infection." (PMID 29704005, 2018). "During the in vitro macrophage infection, unlike TNF-α, our results indicated that VEGF production is significantly induced by the EPTB-isolated strains compared to PTB strains." (PMID 29515555, 2018). "Meanwhile, ΔGntR infection increased the levels of IFN-γ, IL-1β, and TNF-α, indicating ΔGntR could induce the secretion of inflammatory but not anti-inflammatory cytokines IL-10." (PMID 29435171, 2018). "Consequently, the level of ROS and inflammatory cytokines, including IL-6 and TNFα, elevated during PAO1 infection, and their production altered as a result of the genetic manipulation of gp91phox and NF-κB p65, as well as NAC treatment." (PMID 30050663, 2018). "Together, these data suggest that although AZ monotherapy probably does not prevent new HP infection or eradicate existing infection, it likely downregulates the host’s immune responses and dampens macrophage responses and Th1 immunity related to TNF pathways." (PMID 28558695, 2017). "In fact, this outcome was restricted to treatment prior to infection, but not when TNF was added after infection." (PMID 28877735, 2017). "Infection of macrophages with low MOI (MOI 3) was not able to stimulate RIPK1-dependent cell death in the presence of TNFα." (PMID 28892415, 2017).
infection (continued). "In the Mtb-challenged mice, the two vaccinated groups with Mpg as the vaccine module, groups III and IV, secreted significantly higher levels of TNF-α compared to the other groups without Mpg as the vaccine module, groups I and II at 8 weeks after infection." (PMID 29123166, 2017). "Given the marked elevation of transcripts for proinflammatory cytokines (IFN-γ and TNF-α) and T-cell recruiting signals (CXCL9 and CXCR3) in infected brains, we decided to focus on lethal infection, especially vascular/cellular activation and leukocyte recruitment." (PMID 28742087, 2017). "The TNF-α levels in asthmatic/A(H1N1)pdm09 mice increased to 188.5 pg/mL at 3 days post-infection, which was the highest for all groups, and levels remained high at 7 days post-infection (p = 0.33)." (PMID 28831046, 2017). "Second, any increase in self-produced TNF-α (e.g., during infection) does not elicit any anti-TNF-α antibody response in immunized subjects." (PMID 29184553, 2017). "The CD11b+ F4/80+ Ly6C+ GR1+ subpopulation expanded during infection and an increased frequency was found in TNF KO mice, but not in tmTNF KI mice, suggesting that tmTNF, but not solTNF regulates their expansion in the pleural cavity of infected mice." (PMID 28890718, 2017). "Notably, TNF-α and CCL4 levels were significantly lower during Opal524R infection at days 1 and 2 postinfection." (PMID 29138302, 2017). "fail to induce tumor necrosis factor alpha (TNF-α), whereas Omp25 null mutants of Brucella suis (Δomp25 B. suis) exhibit the ability to activate human macrophages to secrete TNF-α, suggesting that Omp25 is involved in inhibition of TNF-α production during infection of human macrophages." (PMID 28694807, 2017). "IFN-α producing pDC always co-produced TNF and infection did not change the proportion of pDC producing TNF alone." (PMID 28572564, 2017). "Indeed, at day 14 post-infection, the amounts of IFN-γ were 100-fold higher in TNF KO than in WT mice." (PMID 28890718, 2017). "Infected epithelial cells produced tumour necrosis factor-α (TNF-α) and IL-6 and the levels of these cytokines were significantly decreased in the presence of the P2X7R inhibitor implicating P2X7R in the production of infection-induced cytokines." (PMID 27559003, 2017). "There have been a few reports showing an increase in the TNF response, in absence of B cells, during infections." (PMID 29209313, 2017). "Whereas CD107a and TNFα continued to be upregulated on KIR3DL01+ and KIR3DL01-05- cells, the percentage of KIR3DL05+ NK cells expressing these antigens declined to baseline levels by week six post-infection." (PMID 28708886, 2017). "Notably, 1–2 h after infection, TAGLN2−/− mice showed higher plasma levels of TNF-α, IL-6, IL-1β, and IL-12 than wild-type mice." (PMID 28821818, 2017). "In the present study, we report that elevated levels of TNFα, a key inflammatory cytokine, in the hippocampus after TMEV infection may mediate the excitotoxic effects through the TNFR1-mediated pathway and contribute to acute seizures." (PMID 28497109, 2017). "Five days post infection with T. spiralis, chitosan appeared to influence the levels of myeloperoxidase (MPO) and cytokines in mice: higher levels of MPO, MCP-1, TNF-α, IL-12p70, IL-6, IL-10 and TGF-β were found in infected mice treated with chitosan compared to those who were not." (PMID 29156562, 2017). "To further investigate whether KLF5 is an effector of TNFRSF11a and whether KLF5 plays a role in TNF-α-induced CC cell functions, we overexpressed KLF5 in HeLa cells through infection with a specific adenovirus (Ad-KLF5)." (PMID 29146991, 2017). "At 24 h post-infection, S. aureus infection without antimicrobial treatments showed a significant (P < 0.05) increase in TNF-α and IL-6 compared to snipped only glands with no S. aureus inoculation." (PMID 29255451, 2017).
infection (continued). "Relative to NMI, in vitro infection of primary human myeloid cells by NMII results in production of more pro-inflammatory cytokines, such as tumor necrosis factor (TNF), interleukin-12p70 (IL-12p70) and interleukin-1ß (IL-1ß), but ultimately both strains replicate similarly." (PMID 28278296, 2017). "Given the hypothesized role of TNFα in AMPAR trafficking and the observed increase in mEPSC amplitudes after TMEV infection, we evaluated hippocampal AMPA receptor expression using a cell-surface biotinylation assay in mice treated with TMEV." (PMID 28497109, 2017). "We observed that infection with the Toledo virus containing the UL/b’ region led to greater NF-κB activation after TNFα treatment than infection with the Towne virus lacking this region." (PMID 28570668, 2017). "ATG7 silencing did not affect priming, as shown by the lack of effect in either WT or pearl DCs on TNFα secretion after STm infection or on pro-IL-1β production after stimulation with LPS-beads." (PMID 29253868, 2017). "Lack of IL-17 or neutralization of TNF-α prevented infection-triggered exacerbation of allergic pulmonary disease." (PMID 29184554, 2017). "However, at day 2 and day 4 after infection, the antiviral IFN-β and proinflammatory IL-6/TNFα response to flu infection was significantly inhibited in CS-exposed WT mice." (PMID 28865477, 2017). "We analysed IFN-γ, granzyme B, TNF-α and IL-10 levels in PBMC from individuals cured of CL (CCLm), or with a probable asymptomatic L. major (HHRLm) or L. infantum (HHRLi) infection as well as in naïve control subjects (HLR), following stimulation with rLmlRAB or rLmlRABC." (PMID 28416006, 2017). "There was significant induction of bronchial IFN-γ, CXCL11/ITAC, CXCL10/IP10, IL-15, IL-10, TNFα and IL-5 during infection in allergic asthmatics (all P < 0.05), but not in healthy controls." (PMID 28373098, 2017). "TNF−/− mice, which are very sensitive to virulent M. tuberculosis H37Rv infection, were used as a positive control of total infection in the absence of functional TNF." (PMID 29184553, 2017). "With the model of M. tuberculosis infection, TNF neutralization by TNFKi vaccination did not increase the sensitivity to the pathogen, but TNF−/− mice died during the early phase of infection." (PMID 29184553, 2017). "Both infected and uninfected BMDM lacked defined M1/M2 polarization, and infection resulted in production of moderate amounts of TNF and nitric oxide." (PMID 28278296, 2017). "Also, there were onefold to threefold more TNF-α and IL-6 detected in BALF from Trim29-KO mice, as compared to that in WT mice on day 1 or day 3 post infection." (PMID 29038422, 2017). "The reduced TNF-α concentrations are not likely to result from a reduced infection stimulus, because the bacterial load was similar in all groups during the first 24 hpi." (PMID 28611405, 2017). "Concerning TNF-α/IL-4 balance, low FEC with elevated serum antibodies and IL-4 could prove the presence of infection." (PMID 28717322, 2017). "Shedding of TNF-α from T cells was also not required for listeria control during primary and secondary infection." (PMID 28877252, 2017). "Knockdown of salusin-β with Ad-Salusin-shRNA dose- and time-relatedly reduced salusin-β, IL-1β, IL-6 and TNF-α mRNA levels, and NOX2 protein and 4-HNE levels in HG-treated H9c2 cells, reaching its maximal effects at the multiplicity of infection (MOI)=100 treated for 24 h." (PMID 28333148, 2017). "Neutralization of IL-17 or TNF-α but not IL-6 resulted in accelerated clearance of M. catarrhalis and effectively prevented infection-induced exacerbation of AAI." (PMID 29184554, 2017). "Considering that TNF-α is involved in PMN activation and priming of responses to secondary stimuli, we would speculate that the infection of bronchial cells with Mtb could modulate PMN effector responses to a second stimulus." (PMID 28852268, 2017).
infection (continued). "In this present study, we did not observe reduction in the circulating TNF under carvedilol therapy when the evaluation was done at 60 days of infection." (PMID 28377930, 2017). "But upon H37Rv infection, the treated cells failed to release adequate levels of TNF-α (276.5 ± 19.94 pg/mL) as compared to untreated infected cells (675.6 ± 87.86 pg/mL)." (PMID 29067283, 2017). "Immunohistochemistry of liver sections to investigate the cellular composition of microabcesses after 4 days of infection revealed an increased accumulation of neutrophils (Ly6G) in TNF−/− and etanercept-treated mice but not TNFKi, KLH, and PBS mice." (PMID 29184553, 2017). "The levels of IFN-γ, IL-4, IL-5, IL-6 and TNF-α were measured in the plasma of HP and non-HP PbNK65 1556Cl1-infected Hsd11b1Del/Del and WT mice at 21 to 24 days (HP) or 28 days (non-HP) after infection." (PMID 29062028, 2017). "Under high glucose conditions (50 mmol/L), siTIPE2 infection exacerbated the increased TNF-α and IL-6 concentrations in differentiated THP-1 cells, and Ad-TIPE2 infection reversed the increased TNF-α concentration, while Ad-TIPE2 infection had no obvious effect on the increased IL-6 release." (PMID 28626770, 2017). "This suggests lymphocyte apoptosis during ZEBOV infection is not due to direct viral replication but rather inflammatory mediators, such as TNFα, nitric oxide, and reactive oxygen species." (PMID 29123522, 2017). "Notably, we observed upregulated mRNA expression levels of IFNα/β, IL6, TNF and several chemokines as CXCL10 or CXCL11 after USUV infection." (PMID 28873445, 2017). "Multiple inflammatory cytokines, including TNF-α, IL-6, IL-1β, IFN-γ, IL-17, and VEGF, disrupt BBB and TJ integrity in BMECs, and inflammatory cytokine signaling at the BBB during infection facilitates leukocyte trafficking into the CNS, which is essential for the clearance of many pathogens." (PMID 29403485, 2017). "However, infection with L. infantum resulted in an increased expression of FoxP3, CD4+, TGF-β, IL-10, TNF-α and IFN-γ in the colon and jejunum and a reduction of CD8+ and IL-4." (PMID 27094260, 2017). "In Hsd11b1Del/Del mice, only IL-4 and TNF-α were significantly increased in response to the infection (respectively, p = 0.0061, 0.0061), and non-significant trends were noted for IFN-γ, IL-5 and IL-6 (respectively, p = 0.103, 0.109, 0.103)." (PMID 29062028, 2017). "Infection of primary monocytes revealed that neither IFNβ nor TNF production was dependent on hemolysin." (PMID 29042860, 2017). "Additionally, we compared TNF-α, IL-10, and IL-6 levels between mild and severe cases of ANDV-infection." (PMID 28708900, 2017). "Furthermore, as in the model of SCI, in which acute inflammatory response occurs rapidly in the CNS, the protein levels of TNFα and other inflammatory cytokines increase rapidly in the hippocampus after TMEV infection." (PMID 28497109, 2017). "Infection with the three heat‐killed P. aeruginosa strains, wild‐type PA7, isogenic mutant ΔpumA or wild‐type PA14 resulted in significant induction of NF‐κB translocation into the nucleus, although to a lower level than TNFα‐treated cells." (PMID 28483816, 2017). "With Archimed software quantification, during early infection, the lung granuloma surface area was increased but not significantly in TNF−/− and etanercept-treated mice." (PMID 29184553, 2017). "Furthermore, changes in type I IFN, IL-6, IL-8, TNF-α, MCP-1 and IP-10 production were observed during concomitant infections." (PMID 28644900, 2017). "This suggests that TNF modulates the overall magnitude of the CD8+ T cell response but does not affect the recruitment of CD8+ T cells to the site of infection." (PMID 28886201, 2017). "Yet, in the absence of IL-17 and/or TNF-α, infection-triggered lung inflammation as well as exacerbation of AAI was very mild and resulted in accelerated clearance of pathogenic airway bacteria, emphasizing the inflammation promoting role of these cytokines." (PMID 29184554, 2017).
infection (continued). "Our data showed that TNF increases intracellular parasite growth and accelerates trypomastigote egression when added to astrocytes prior to infection but not after infection." (PMID 28877735, 2017). "In contrast, levels of TNF, the IL-12p70 heterodimer, and the IL-12p40 subunit were significantly reduced in the BALF at 24 hours post-infection in anti-Gr-1-treated mice, in agreement with a previous study using anti-Gr-1-mediated depletion during pulmonary L. pneumophila infection." (PMID 28384349, 2017). "Whereas the expected exacerbation of the infection was seen in mice treated with anti-TNFα antibodies but no antibiotics." (PMID 28087648, 2017). "In terms of cytokine expression, compound-6 treated mice had significantly higher expression of IL-6 (lung and brain), IL-4 (lung and brain), IFN-γ (lung and brain), TNF-α, IL-β1and IL-12 (lung) when compared to control group (without infection)." (PMID 29133871, 2017). "Host cytokines IL-2, IFN-γ, and TNFα are elevated during infection and have been suggested as markers of active infection, although not specific for TB." (PMID 29237757, 2017). "To examine the effect of LG2055 on inflammatory responses in gingival tissues of mice orally administered P. gingivalis, we examined the IL-6 and TNF-α mRNA levels in gingival tissues and GMCs, and IL-6 and TNF-α secretion in GMCs 1 and 30 days after the final infection." (PMID 28373699, 2017). "This discovery uncouples the role of the TNF pathway in dictating the individual cell fate during infection and identifies the interaction of DVGs with the MAVS-mediated antiviral pathway as a critical factor in defining cell survival upon infection." (PMID 28986577, 2017). "Mice treated with anti-TNF-α antibodies succumb to primary infection, and mice lacking TNF-α receptors exhibit necrosis of brain tissue due to parasite reactivation." (PMID 28424687, 2017). "However, we have previously shown that OTI cells either activated in vivo by infection with HKx31-OVA or in vitro by a 5h peptide stimulation, produce TNF protein prior to IFNγ, which supports the current findings." (PMID 28886201, 2017). "In contrast, Breyne and co-workers (2015) reported that infection of the mouse mammary gland with S. aureus resulted in local induction of IL-1β and IL-6 but not TNF-α." (PMID 28129375, 2017). "In addition, the production of TNF-α, IL-6, and IL-10 was similar between TLR2−/− and WT mice during the early stage of infection (5 dpi)." (PMID 28979269, 2017). "Here, we used this tool to investigate the role of sTNF during the early infection by T. brucei or T. congolense parasites, since this is the stage where the absence of TNF appears to exhibit the most drastic effects." (PMID 28733685, 2017). "Conversely, cluster 4 was enriched for TNF, inflammasome, TLR and NFkB signaling pathways and was associated with TP, TS, and age but not infection." (PMID 28966918, 2017). "Furthermore, YopM from different Yersinia strains reduced the production of proinflammatory cytokines (i.e. Interferon–γ (IFN-γ), Interleukin-1β (IL-1β), Tumor Necrosis Factor-α (TNF-α), Interleukin-15 (IL-15)) in mice at 1–4 days post infection." (PMID 27300509, 2016). "The combination of anti-TNF-α drugs and antibiotic may have little use in the treatment therapy against ST239 infections." (PMID 27446000, 2016). "Multiple cytokines in RDPs, including TNF-α, IL-8, IP-10, MCP-1, MIP-1α, IL-1ra, IL-10, G-CSF, IFN-γ, IL-4 and IL-17, reached peak value in 4 to 5 weeks after infection, whereas only IP-10 and IL-13 in SPDs did so, and lack of TNF-α in SDPs." (PMID 27830756, 2016). "Our experimental results showing that clinically used anti-TNF-α inhibitors can totally abrogate the antiviral activity of TNF-α appear to support those clinical observations and highlight the primary role of TNF-α in host defense against infections." (PMID 27150018, 2016).